APP (amyloid beta precursor protein)
Diseases named in the same sentence as APP in open-access papers (continued):
Sharing a sentence is not in itself a finding about the gene and the disease.
Anxiety (continued). "However, the time spent in the center was significantly higher in APP/Ps1 females compared to males of the same line (p = 0.033, Kruskall-Wallis test), which may indicate sex-dependent differences in anxiety-like behavior." (PMID 41300242, 2025). "Next, we evaluated whether TSA could attenuate anxiety-like behaviors in APP/PS1 mice." (PMID 38572429, 2024). "Finally, the hypothesis that we think is most likely is that a combination of learning and memory dysfunction and increased anxiety is driving the impairments in MWM performance in the APP mice." (PMID 37950055, 2023). "In addition, continuous four-month feeding of 2% and 4% date fruit pellets to APP-transgenic Alzheimer’s mice resulted in considerable memory improvement, decreased anxiety-like behavior, reversal of spatial learning capacity, position discrimination learning capability, and motor coordination." (PMID 36840284, 2023). "We sought to clarify whether activation of VTAVgat neurons could alleviate anxiety in APP/PS1 mice." (PMID 37032820, 2023). "And treadmill exercise may ameliorate anxiety-like symptoms by regulating tau and APP." (PMID 36106141, 2022). "Furthermore, METH also can increase tau phosphorylation and APP processing, which may be responsible for the development of the anxiety-like symptoms in this model." (PMID 36106141, 2022). "Thus, although the measures of anxiety in the elevated zero maze and open field are distinct, they revealed an APP × APOE interaction at 6 and 18 months in males and females and highlight the importance of including more than one test to assess measures of anxiety." (PMID 35299942, 2022). "Therefore, the increased freezing to context induced by β-AR agonist may have emerged from β-AR agonist induced changes in innate anxiety levels of APP/PS1." (PMID 33441593, 2021). "However, compared with the WT mice, an increased anxiety of p47phox-deficient mice was observed, and p47phox deficiency dose not aggravate the anxiety of APP/PS1 mice." (PMID 33183342, 2020). "Moreover, this anxiety-like behavior was prevented by subchronic JuA treatment in APP/PS1 mice." (PMID 30872728, 2019). "APPSwe/PS1dE9 (APP/PS1) transgenic mice overexpressing the human mutated APP with Swedish mutation (APP695Swe), and mutant human presenilin 1 with exon 9 deletion (PSEN1dE9), are characterized by age-related memory deficit, anxiety, hyperactivity, and impaired social interaction." (PMID 30352982, 2018). "The increased activity exhibited by APP/PS1 mice within the arena may not be a result of increased anxiety which is associated with increased defecation and thigmotaxis during the OFT." (PMID 28741167, 2017). "In open field and dark–light tests, APP/PS1/Hif-p4h-2gt/gt mice maintained their behavior during aging, whereas controls showed a change by 60% to 80% in exploratory activity and anxiety parameters from 6 to 12 months." (PMID 40609789, 2025). "NC-treated APP/PS1 mice exhibited preserved object recognition memory and reduced anxiety-like behaviours, contrasting with deficits observed in untreated transgenic controls." (PMID 40862772, 2025). "The number of exits to the lit box was significantly lower in APP/PS1 mice than in WT mice (p = 0.04, Holm–Šídák’s test), further suggesting an increase in anxiety-like behavior in the mutants." (PMID 40801602, 2025). "Serpina3n inhibition attenuated the anxiety and increased the number of neurons in the hippocampal CA1(cornu ammonis) region of APP/PS1 mice." (PMID 39519278, 2024). "Taken together, six-month-old APP/PS1 mice exhibited anxiety- and depression-like behaviors under the OFT, MBT, EPM, ST, TST, and FST, and treadmill exercise effectively alleviated these behaviors in APP/PS1 mice." (PMID 39744519, 2024). "Thus, we speculated that TSA might also relieve anxiety and depressive behavior in APP/PS1 mice." (PMID 38572429, 2024).
Anxiety (continued). "The anxiety index did not reveal any statistically significant differences between the animal groups (p > 0.05); however, there is a tendency for both APP-positive animals and WT animals treated with SEM to exhibit reduced anxiety-related behavior." (PMID 39767596, 2024). "Chronic intermittent therapy with these compounds in the pre-symptomatic APP/PS1 transgenic mice partially reversed the long-term recognition memory impairment and decreased anxiety-like behavior." (PMID 38675490, 2024). "After three months of treatment, APP/PS1 mice’s motricity and anxiety were assessed with an infrared actinometer and the elevated plus maze (EPM), respectively." (PMID 36982363, 2023). "Nevertheless, sleep completely relieves SDS-induced anxiety in APP/PS1 mice, and the activation of VTAvgat neurons alleviates SDS-induced anxiety in APP/PS1 mice." (PMID 37032820, 2023). "Our results showed that acute SDS led to anxiety in APP/PS1 mice, as evidenced by increased anxiety-related behaviors in the open field and elevated plus-arm tests." (PMID 37032820, 2023). "The APP/PS1 mouse presents learning and memory dysfunction at 6–8 months, Aβ depositions and neuroinflammation at 6 months, increased anxiety at 12 months of age and senile plaques at 8 months, resembling the symptoms of early-onset familiar AD." (PMID 37698780, 2023). "When measures of anxiety were assessed in the elevated zero maze in males, there were effects of APOE, APP, and an APP × APOE interaction for the percent time spent in the open areas." (PMID 35299942, 2022). "In the APP/PS1 mouse model of AD, showing anxiety-like behavior, the photo stimulating the pBLA-vCA1 circuit ameliorated the anxiety in a Calb1-dependent manner." (PMID 35637434, 2022). "In males, measures of anxiety in the elevated zero maze revealed an APP × APOE interaction at the 6-month time point, measures of anxiety in the open field revealed an APP × APOE interaction at the 18-month time point." (PMID 35299942, 2022). "In the 9-month-old APP/PS1 mouse, VB reduced anxiety, improved memory and spatial cognition, suppressed the deposition of Aβ and tau protein phosphorylation, and decreased the overexpression of 4-HNE and MANF in the hippocampus." (PMID 33070776, 2020). "Given that anxiety can exacerbate memory deficits in AD20,26, we administered the Barnes maze (BM) to test spatial cognitive functions in APP/PS1 mice." (PMID 31924799, 2020). "The presence of anxiety-related behaviour in the APP/PS1 mouse model is thus widely discussed and our findings support the findings of unchanged anxiety-levels, at least up to 18 months of age." (PMID 27814403, 2016). "Behavioural symptoms in the APP/PS1 mouse model, which are correlated to neuropsychological clinical symptoms, include disturbances in locomotor activity, anxiety, aggression, and social behaviour." (PMID 27814403, 2016). "Consistently with literature data, 6 months old APP/PS1 mice displayed significant hyperactivity and anxiety compared to the wt littermates, as shown by both the open field and sociality tasks." (PMID 27724899, 2016). "There are some reports indicating increased locomotion in the APP/PS1 mouse model, and reduced anxiety-like behaviour at 7 months of age." (PMID 27814403, 2016). "Because AD is correlated with both anxiety and incontinence, we wanted to investigate both the affective and the voiding behavior of transgenic APPSL/PS1M146L (APP/PS1) mice, a mouse model of AD." (PMID 26379542, 2015). "This is in contrast to the Tg2576, J20, APP/PS1, and 5xFAD mice, which all were found to have increased anxiety-related behavior in the elevated plus maze task." (PMID 23705774, 2013). "The central residence time was significantly reduced in APP/PS1 mice compared to WT mice, indicating higher anxiety levels; ginseng (P < 0.05) and Ro L (P < 0.01) treatments significantly increased the central residence time, while Ro H showed an increasing trend without reaching significance." (PMID 40066331, 2025).
Anxiety (continued). "APP/PS1 mice spent more time in the central part of the apparatus, the difference was statistically significant at 16 WPI, suggesting decreased anxiety in APP/PS1 animals." (PMID 40214165, 2025). "Prior to and a week after infection, APP/PS1 mice entered open arms rather less often, suggesting more anxious behavior, while 16 WPI, they visited open arms much more often than WT mice, suggesting lower anxiety." (PMID 40214165, 2025). "In addition, insulin also reduces anxiety-related behaviors and improves performance in the reversal MWM test in APP/PS1 mice." (PMID 41146261, 2025). "Significantly reduces the number of Aβ plaques, decreases neuronal apoptosis, and ameliorates mitochondrial dysfunction in astrocytes in the brains of APP/PS1 mice but does not significantly affect anxiety or cognitive function in the mice." (PMID 40778306, 2025). "We found that anxiety-like behavior in OF was increased in female traveled and sham-irradiated APP;E4F mice compared to non-traveled controls." (PMID 39273325, 2024). "Both tests indicated comparable anxiety-related behavior in WT and APP/PS1 mice with and without 15 weeks of treatment." (PMID 39519239, 2024). "Regarding other non-cognitive symptoms, we observed a decreased anxiety-like behavior in APP/PS1 mice, supporting previous studies." (PMID 37698780, 2023). "Furthermore, the anxiety state correlated negatively with sleep duration and NREM percentage and correlated positively with theta power density in APP/PS1 mice." (PMID 37032820, 2023). "Deletion of the AQP4 gene increased hyperactivity, intraneuronal Aβ load and glutamatergic neuron activation, but did not influence working memory or anxiety-like behaviors of 4-month-old APP/PS1 mice." (PMID 36186142, 2022). "We further demonstrate that β-AR agonist per se does not modulate the baseline innate anxiety levels of APP/PS1." (PMID 33441593, 2021). "Control APP/PS1 mice were less inclined to explore the central area of the OFT chamber than WT controls (F3, 34 = 6.642, p < .0001, one‐way ANOVA), suggestive of increases in anxiety‐related behavior." (PMID 31877583, 2020). "In addition to the anxiety, we also evaluated other behaviors such as depressive state with FST or social ability with three-chamber test in the early age of APP/PS1 mice." (PMID 32398165, 2020). "We also found a highly differential protein network between the aBLA and pBLA, with disorganised firing of a/pBLA–vCA1 inputs in APP/PS1 mice, and the optogenetic stimulation of the pBLA–vCA1Calb1+ circuit attenuated anxiety behaviours and spatial memory deficits in a Calb1-dependent manner." (PMID 31924799, 2020). "In conclusion, the APP/PS1 mice exhibited higher neuronal excitability and an impairment in hippocampal neurogenesis at the early stage, and these changes were accompanied by increased locomotion and lower anxiety." (PMID 31094092, 2019). "Thus, in APP/PS1 mice, the chronic treatment with Quetiapine for 7 and/or 10 months normalized the anxiety-like behavior observed in the maze, minimized memory deterioration, and decreased Aβ plaques in the brain." (PMID 31607916, 2019). "This is in accordance with the findings of another study on APP/PS1 mice back‐crossed for at least five generations onto the SAMP8 background strain, which also demonstrated in hyperactivity and lower levels of anxiety in the elevated plus maze by 6 months of age." (PMID 28160413, 2017). "In elevated plus maze (EPM) anxiogenic behavior was observed in Tg 2576 mice, but anxiolytic behavior was noted in other types of transgenic mice (mutant PS1 and PS2 genes) and still in transgenic mice overexpressing APP, anxiety status was not changed." (PMID 26880859, 2016). "To determine whether the transgenic mouse model of AD, APP/PS1 (APPSL/PS1M146L) mouse, shows alteration of the urinary bladder function and anxiety, as for patients with AD, we examined the urinary marking behavior in relation to affective behavior." (PMID 26379542, 2015).
Anxiety (continued). "The APP/PS1 KI mice do not exhibit anxiety-related behavior, as they showed normal exploration of the center of the open field chamber." (PMID 23705774, 2013). "We report here that the APP/PS1 KI mouse shows no motor deficits or abnormal anxiety levels at any of the ages tested." (PMID 23705774, 2013). "There were also no anxiety-related behavior deficits seen at any age in the APP/PS1 KI mice in the elevated plus maze tasks." (PMID 23705774, 2013). "Moreover, LY3000328 injection in the hippocampus did not induce anxiety‐like behavior compared to vehicle in APP/PS1 transgenic mice." (PMID 39453382, 2025). "However, the present study failed to observe any obvious change in anxiety levels in either 5-month-old or 9-month-old APP/PS1 mice treated with Xn or Mem." (PMID 39114364, 2024). "Altogether, the results of the behavioral experiments indicated that APP/PS1 mice may not display age‐dependent anxiety‐like behavior." (PMID 38606360, 2024). "However, it was observed that there was significantly less anxiety-like behavior in traveled female APP;E4F mice who were sham-irradiated compared to non-traveled female controls (p = 0.0268)." (PMID 39273325, 2024). "In this regard, although sleep plays a restorative function after SDS, it may not fully relieve anxiety in APP/PS1 mice compared to wild-type mice." (PMID 37032820, 2023). "The effect of D-ribose was not affected after taking BBR or Midivi-1, suggesting that BBR could not relieve the anxiety induced by D-ribose in APP/PS1 mice." (PMID 36982968, 2023). "L-DL OE did not affect locomotor activity and anxiety in APP/PS1 mice." (PMID 34551807, 2021). "Furthermore, using OFT, we demonstrate that vH β-AR agonist infusion per se does not interfere with innate anxiety responses of APP/PS1 mice." (PMID 33441593, 2021). "However, we still do not know the dynamics and the nature of learned fear versus innate anxiety in APPswe/PS1dE9 mice at an age where there is constitutive overexpression of APP and PS1 genes without β-amyloid deposition." (PMID 33441593, 2021). "By subjecting WT and APP and mice to a battery of behavioral tasks at P60, P90, and P180, we determined that APP mice were hyperactive by P60, developed episodic working memory deficits by P90, and exhibited anxiety‐like behavioral traits but no spatial learning impairment by P180." (PMID 32557778, 2020). "In the elevated plus maze test, APP mice travelled a longer distance in the open arms compared to wild-type (WT) mice 4, but antroquinonol did not significantly alter this anxiety behavior within the groups." (PMID 26469245, 2015). "This led us to perform open field experiment with APP/PS1 mice following vCA1 β-AR agonist infusion to investigate whether the β-AR agonist potentiated the consolidation of the fear memory trace, or enhanced innate anxiety levels to promote avoidance behaviour." (PMID 33441593, 2021). "Although the latency to exit the lit box was not significantly different (p = 0.26, Kruskal–Wallis test), APP/PS1 mice showed a trend toward longer exit latency, suggesting that anxiety-like behavior was not fully normalized by NC treatment." (PMID 40801602, 2025). "In APP × PS1 mice, CBD administration rescued cognitive deficits measured by object recognition and social recognition memory without affecting anxiety behavior." (PMID 39456229, 2024). "In contrast, 5XFAD, but not APP/PS1, mice spent more time in the center of the arena (an indicator of reduced anxiety) than WT control mice." (PMID 39216535, 2024). "Together, these results suggest that hyperactivity occurs in a subset of 4-month-old APP/PS1 mice, which is not related to either cognitive performance or anxiety-like extent." (PMID 36186142, 2022). "RD2 improved cognitive performance of APP/PS1 mice already after a short, three weeks, treatment and reduced insoluble Aβ(x-42) levels in the brain without a negative impact on activity or anxiety." (PMID 29176708, 2017).
Anxiety (continued). "Consistent with our findings, however, there are also studies reporting no changes in OF activity in APP/PS1 mice at 7 months of age, at 10–15 months of age, and no changes in anxiety-related behaviour at 10–15 months of age." (PMID 27814403, 2016). "In contrast, expression of LIMK1-EGFP in APP/PS1 mice significantly improved social recognition memory in both three-chamber and five-trial repeated exposure tests, without affecting locomotor activity or anxiety-like behavior." (PMID 34315506, 2021). "The ablation of OPCs has been shown to produce anxiety‐like behavior within 7 days, and while the electrophysiological response of OPC is altered by P100 in APP mice, any reduction detected in OPC density is minor, and APP mice do not display an anxiety‐like phenotype until P180." (PMID 32557778, 2020). "In a similar study, CBD was provided as pellets to APP × PS1 mice at the age of 2.5 months for 8 months and could prevent the development of social recognition memory deficits without affecting Aβ load, oxidative damage, or anxiety behavior." (PMID 39456229, 2024).